SF3A1 (splicing factor 3a subunit 1)
Description:
Component of the 17S U2 SnRNP complex of the spliceosome, a large ribonucleoprotein complex that removes introns from transcribed pre-mRNAs. The 17S U2 SnRNP complex (1) directly participates in early spliceosome assembly and (2) mediates recognition of the intron branch site during pre-mRNA splicing by promoting the selection of the pre-mRNA branch-site adenosine, the nucleophile for the first step of splicing. Within the 17S U2 SnRNP complex, SF3A1 is part of the SF3A subcomplex that contributes to the assembly of the 17S U2 snRNP, and the subsequent assembly of the pre-spliceosome 'E' complex and the pre-catalytic spliceosome 'A' complex. Involved in pre-mRNA splicing as a component of pre-catalytic spliceosome 'B' complexes.
Synonyms: SAP114; SF3a120; PRPF21; Prp21
Tractability: Small molecule: a structure with a bound ligand is known. PROTAC: UniProt records ubiquitination sites on it; ubiquitination databases record sites on it; its protein half-life has been measured.
Target class: Other nuclear protein
Gene: Protein-coding gene on chromosome 22 (30,331,988 to 30,356,919, reverse strand). Ensembl gene ENSG00000099995.
Subcellular location: Nucleus; Nucleus speckle
Subcellular location (Human Protein Atlas): Nuclear speckles; Nucleoplasm
Pathways (Reactome):
Metabolism of RNA: mRNA Polyadenylation; mRNA Splicing - Major Pathway
Chromatin organization: CHD1 and CHD2 subfamily
Disease: Dengue Virus-Host Interactions
Gene Ontology:
Molecular function: protein binding; RNA binding
Biological process: mRNA processing; mRNA splicing, via spliceosome; U2-type prespliceosome assembly; mRNA 3'-splice site recognition; spliceosomal snRNP assembly; mRNA cis splicing, via spliceosome; RNA processing
Cellular component: catalytic step 2 spliceosome; nuclear speck; nucleoplasm; nucleus; precatalytic spliceosome; spliceosomal complex; U2 snRNP; U2-type catalytic step 1 spliceosome; U2-type precatalytic spliceosome; U2-type prespliceosome; U2-type spliceosomal complex
Genetic constraint (gnomAD): Loss-of-function variants: 11 observed, 80.38 expected, observed/expected ratio (o/e) 0.14, 90% interval 0.085 to 0.23. The upper end of that interval is the gene's LOEUF score, 0.23, which puts it in group 1 of 6, group 1 being the genes least tolerant of losing a copy. Missense variants: 568 observed, 978.95 expected, observed/expected ratio (o/e) 0.58, 90% interval 0.54 to 0.62. Synonymous variants: 386 observed, 369.83 expected, observed/expected ratio (o/e) 1.04, 90% interval 0.96 to 1.13.
Homologues: Orthologues: chimpanzee SF3A1 (100% identical), macaque SF3A1 (99% identical), dog SF3A1 (99% identical), guinea pig SF3A1 (99% identical), mouse Sf3a1 (98% identical), rat Sf3a1 (98% identical), rabbit SF3A1 (97% identical), pig SF3A1 (88% identical), tropical clawed frog sf3a1 (88% identical), zebrafish sf3a1 (84% identical), Drosophila melanogaster Sf3a1 (53% identical), Caenorhabditis elegans prp-21 (37% identical).
Diseases named in the same sentence as SF3A1 in open-access papers:
SF3A1 is named in the same sentence as 30 diseases in open-access papers, as found by Europe PMC text mining. Sharing a sentence is not in itself a finding about the gene and the disease. The quoted sentences say what the papers report.
breast carcinoma (6 papers, 2013 to 2021). "Polymorphisms in SF3A1 have been found to be associated with slightly higher colorectal cancer risk and breast cancer." (PMID 28589855, 2017). "SF3A1 is located in 22q12.2, where has been reported to be associated with susceptibility of lung cancer, breast cancer and inflammatory bowel disease by genome-wide association studies." (PMID 26079486, 2015). "SF3A1 has been reported to be related to susceptibility of breast cancer and lung cancer." (PMID 31844595, 2019).
colorectal cancer (6 papers, 2015 to 2026). A primary or metastatic malignant neoplasm that affects the colon or rectum. "In conclusion, SF3a1 could serve as a promising prognostic biomarker and therapeutic target for specific cancer types, including prostate cancer, colorectal cancer and hepatocellular carcinoma." (PMID 40302801, 2025). "However, the role of SF3A1, one key component of the mRNA splicing machinery, on colorectal cancer (CRC) risk was still not elucidated." (PMID 26079486, 2015). "In this study, we demonstrate that downregulation of Splicing factor 3A1 (SF3A1) markedly suppressed the proliferation of colorectal cancer (CRC) cells, with minimal cytotoxicity observed in non-cancerous epithelial cells." (PMID 41683622, 2026). "Interestingly, Western blotting revealed a decrease in cyclin D1 in colorectal cancer cells (HCT116 cells) and pancreatic cancer cells (SUIT2 cells) but not esophageal cancer cells (OE33 cells) by the downregulation of SF3A1." (PMID 34202873, 2021).
lung carcinoma (3 papers, 2015 to 2019). "Depletion of SRSF1 in human A549 lung cancer cells reduces IFN-β through the expression of alternative IRF3 spliced variants, while SF3A1 silencing leads to a decreased induction of pro-inflammatory cytokines by promoting an alternative splice form of MyD88." (PMID 27454487, 2016).
pancreatic cancer (3 papers, 2015 to 2021). "Previous studies indicated that two SNPs (rs5994293 and rs9608886) of SF3A1, locating to the region of 22q12.2, were strongly correlated with pancreatic cancer." (PMID 31552163, 2019). "A two-stage case-control study was conducted to examine the association between six candidate U2-depedent spliceosome genes (SRSF1, SRSF2, SF3A1, SF3B1, SF1 and PRPF40B) and pancreatic cancer (PC)." (PMID 26498691, 2015).
Ewing sarcoma (2 papers, 2021 to 2025). A small round cell tumor that lacks morphologic, immunohistochemical, and electron microscopic evidence of neuroectodermal differentiation. "Silencing SF3B1 or SF3A1 reduced EWS-FLI1 protein activity and Ewing sarcoma cell survival; and inhibition of SF3B1 with a small molecule resulted in mis-splicing of EWS-FLI1 and loss of Ewing sarcoma cell viability." (PMID 34065983, 2021).
head and neck cancer (2 papers, 2015 to 2020). A primary or metastatic malignant neoplasm affecting the head and neck. "Population studies have revealed that SF3A1 expression may be up-regulated in head and neck cancers, rectal carcinomas, and human non-small and small-cell lung cancers." (PMID 26498691, 2015).
ovarian carcinoma (2 papers, 2019 to 2025). A malignant neoplasm originating from the surface ovarian epithelium. "And the mutation of SF3A1 were involved in some cancers, including esophageal adenocarcinoma, osteosarcomas, ovarian carcinoma and gastric cancer." (PMID 31844595, 2019).
rectal carcinoma (2 papers, 2015 to 2020). A malignant epithelial neoplasm that arises from the rectum and invades through the muscularis mucosa into the submucosa. "SF3A1 expression was found to be up-regulated in rectal carcinomas as well as in other cancers." (PMID 31963158, 2020).
adenoma (1 paper, 2016). A neoplasm arising from the epithelium. "The gene SF3A1 was studied in relation to CRC adenomas without finding any correlation to this gene." (PMID 26872740, 2016).
asthma (1 paper, 2021). "Also, in the context of development of severe asthma, KEGG enrichment of the spliceosome (mRNAs; SF3A1, SNRPE, SF3B4) has been observed." (PMID 34068174, 2021).
autoimmune disorders (1 paper, 2025). "The correlation between SF3a1 and cancers, as well as other immune-related diseases, including autoimmune disorders and infections, suggests that it could serve as a promising prognostic marker and therapeutic target." (PMID 40302801, 2025). "Additionally, SF3a1 also participates in autoimmune disorders and infectious diseases by regulating expression of isoforms of inflammatory factors." (PMID 40302801, 2025).
breast tumor (1 paper, 2010). "The first dataset includes relative expression levels of 6 reference genes (ACTB, GAPDH, MRPL19, PSMC4, PUM1, and SF3A1) quantified in 80 breast tumor samples." (PMID 20470420, 2010).
hyperplastic polyp (1 paper, 2016). A polyp found mainly in the stomach and colon. "Finally, if also the patient (Co-657) with five hyperplastic polyps at an age of 73 years was considered a gene carrier, yet another three genes (SF3A1, GAL3ST1, TRIOBP) could be excluded." (PMID 26872740, 2016).
myotonic dystrophy (1 paper, 2023). An inherited progressive disorder affecting the muscles. "Interestingly, a similar sharp cut-off between alternative and constitutive splicing has been reported in myotonic dystrophy (DM1/DM2) with similar genes being affected, namely CELFs, MBNLs, NOVA, SMN1/2 and SF3A1, among others." (PMID 36282542, 2023).
cancer (10 papers, 2013 to 2025). A tumor composed of atypical neoplastic, often pleomorphic cells that invade other tissues. "In this review, we present the findings of SF3a1 from protein structure, biological function to strong associations with human diseases including cancer." (PMID 40302801, 2025). "In conclusion, SF3a1 mutations are significantly correlated with the risk and prognosis of various cancers, particularly those of the digestive system, although some discordance exists, and further functional experiments are needed." (PMID 40302801, 2025). "We performed a hospital-based case-control study containing 801 CRC patients and 817 cancer-free controls to examine the association between SF3A1 polymorphisms and CRC risk in a Chinese population." (PMID 26079486, 2015). "Collectively, these findings suggested the link between SF3A1 and cancer risk, and emphasized a need of additional researches for the association of SF3A1 polymorphisms and CRC risk." (PMID 26079486, 2015). "As a member of splicing complex, SF3A1 has been implicated in various cancers." (PMID 26079486, 2015). "Research on SF3a1 has been more abundant and in-depth in cancers compared to hematologic malignancies." (PMID 40302801, 2025). "Several functional and mechanistic studies have elucidated the potential contribution of SF3a1 to the pathogenesis of cancers including CRC, PC and HCC." (PMID 40302801, 2025). "Our functional assay showed that SF3A1 strongly promoted the cell growth in cancer cells (HCT116, SUIT-2, OE33 and KYSE-70 cells) specifically, indicating that SF3A1 is a viable therapeutic target for tumor therapy." (PMID 34202873, 2021). "Thus, genetic variants rs2074733 in SF3A1 may be involved in other cancer types beyond PC." (PMID 26498691, 2015). "Here, we selected other six U2-dependent spliceosome genes previously shown to have cancer-associated mutations (SRSF1, SRSF2, SF3A1, SF3B1, SF1 and PRPF40B), and screened 17 putative tag single nucleotide polymorphisms (tagSNPs) in these genes." (PMID 26498691, 2015). "Aberrant expression of SF3a1 and related AS events may serve as biomarkers or therapeutic targets for related diseases, especially cancers such as PC, CRC and HCC." (PMID 40302801, 2025). "Several aberrantly expressed proteins in various cancers have been found to be regulated by SF3a1." (PMID 40302801, 2025). "The abnormal expression of splicing factors, including ESRP1 and SF3A1, are known to modify splice site selection, thus generating mRNA isoforms that contribute to the development, progression and therapeutic response of cancers." (PMID 31963158, 2020). "To investigate the roles of SF3A1 polymorphisms in contributing to the susceptibility of CRC, we performed an association analysis of rs5753073, rs2839998, rs10376 and rs2074733 in 801 cases and 817 cancer-free controls in a Chinese population." (PMID 26079486, 2015). "Along with SFRS4 (number 13 in the top list of “universal” reference genes), three genes that participate in pre-mRNA splicing and processing pathways (SF3A1, SF3B2, and SFRS3) are present in the top 10 of promising pan-cancer RGs." (PMID 30881377, 2019). "Our cDNA array analysis showed that SF3A1 is not dramatically increased in cancer cells, suggesting that post-translational modification rather than the augmentation of SF3A1 is also associated with cancer cell progression." (PMID 34202873, 2021).
tumor (4 papers, 2015 to 2025). "The aberrant expression of splicing factors, such as SF3A1, can modify splice site selection, and hence modulate alternative splicing of tumor promoters or suppressors, resulting in the formation of mRNA isoforms." (PMID 31963158, 2020). "Collectively, SF3a1 is a component of the SF3a complex within the spliceosome, functions as a core regulatory factor in pre-mRNA AS, and plays pivotal roles in multiple biological processes, including tumor development." (PMID 40302801, 2025). "Given the key functions of SF3a1 in spliceosome and the extensive regulatory effects of other U2 snRNP components on tumor biology 12, we present a comprehensive overview of SF3a1's structure and biological function, particularly in the context of tumorigenesis." (PMID 40302801, 2025). "SF3a1 was necessary for the retention of exon 7 to exert pro-tumor effects." (PMID 40302801, 2025). "Future studies are warranted to determine whether changes in SF3A1 can alter the splicing of specific oncogenes or tumor suppressors to promote PC." (PMID 26498691, 2015).
hematologic malignancies (2 papers, 2013 to 2025). "The SF3B1 and SF3A1 mRNA splicing factors have also been implicated in the pathogenesis of numerous hematologic malignancies." (PMID 24204290, 2013). "Authoritative studies have shown SF3a1's involvement in hematologic malignancies." (PMID 40302801, 2025).
infectious disease (1 paper, 2025). A disorder directly resulting from the presence and activity of a microbial, viral, or parasitic agent in humans. "SF3a1 has also been implicated in non-tumor immune-related disorders, including autoimmune and infectious diseases." (PMID 40302801, 2025).
SF3A1 also shares sentences with these, for which no sentence is quoted: prostate carcinoma (3 papers); myelodysplastic syndrome (2); non-small and small-cell lung cancers (2); colorectal adenocarcinoma (1); endometrial cancer (1); esophageal adenocarcinoma (1); esophageal cancer (1); gastric cancer (1); hepatocellular carcinoma (1); infection (1); osteosarcoma (1); sarcoma (1).